EGFR (epidermal growth factor receptor)
Diseases named in the same sentence as EGFR in open-access papers (continued):
Sharing a sentence is not in itself a finding about the gene and the disease.
lung adenocarcinoma (continued). "EGFR mutation is the most frequently encountered driver mutation in NSCLC, especially in lung adenocarcinoma." (PMID 34496872, 2021). "The accumulated p62 by autophagy inhibitor, chloroquine has oncogenic functions in EGFR‐TKI resistant lung adenocarcinoma." (PMID 33486901, 2021). "Immunotherapy is considered one of the most important therapeutic strategies for patients with lung adenocarcinoma after the development of epidermal growth factor receptor tyrosine kinase inhibitor (EGFR‐TKI) resistance." (PMID 33305905, 2021). "Together, inactivated c-Src by dasatinib administration sensitized EGFR-mutant lung adenocarcinoma to TKIs." (PMID 34367939, 2021). "Surprisingly, c-Src inactivation through caspase-8 knockdown or dasatinib was able to block the survival-signaling-related tyrosine phosphorylation of EGFR, which, in turn, increased the antitumor activity of TKIs in EGFR-mutant lung adenocarcinoma." (PMID 34367939, 2021). "Compared with previous profiling of PTM immunopeptides, we, for the first time, systematically quantified the largest number of endogenous PTMs of class I-presented peptides in EGFR-mutant lung adenocarcinoma." (PMID 34391887, 2021). "In H358ER erlotinib-resistant human lung adenocarcinoma cell line, with wild-type EGFR the overexpression of Axl was reported, however, the knockdown of Axl in this cell line did not restore sensitivity to erlotinib." (PMID 33806258, 2021). "It has been reported that patients with EGFR-mutant lung adenocarcinoma are more likely to develop brain metastases (39.2% vs. 28.2%; P = 0.038) and meningeal metastases (9.4% vs. 1.7%; P < 0.01) than wild-type patients." (PMID 33575349, 2021). "Here, we describe a patient with bilateral multifocal lung adenocarcinoma harboring a very rare EGFR exon 20 insertion (c.2317_2319dup3; p.H773dup), who has been receiving treatment with afatinib for 4.5 years." (PMID 33575211, 2021). "In particular, we aimed to explore new predictors of therapeutic efficacy and the therapeutic targets of ICI in patients with EGFR‐TKI‐resistant lung adenocarcinoma." (PMID 33305905, 2021). "The success of anti-EGFR therapy in lung adenocarcinoma was probably the stimulus for establishing this concept." (PMID 34502326, 2021). "Further qPCR also revealed that the expression of one FOXO6-eRNA was significantly higher in PC9 cell line (EGFR mut-type) than that in other two EGFR wide-type lung adenocarcinoma cell lines (A549 and NCI-H1299)." (PMID 33042282, 2020). "We compared the expression and phosphorylation status of Mig-6 in the EGFR-TKI resistant lung adenocarcinoma (PC9/GR cells) to EGFR-TKI sensitive lung adenocarcinoma (PC9 cells)." (PMID 32552717, 2020). "Univariate and multivariate Cox proportional hazard analysis for mortality in EGFR positive lung adenocarcinoma subjects." (PMID 32053675, 2020). "In lung adenocarcinoma, the combined expression of ARF6, its GEF BRAG2/GEP100 and EGFR is associated with decreased patient survival." (PMID 32426352, 2020). "This study was performed in a cohort of patients with lung adenocarcinoma, showing wild-type EGFR, treated with conventional chemotherapy." (PMID 33167343, 2020). "This retrospective cohort study enrolled patients with advanced lung adenocarcinoma under first-line EGFR-TKIs between 2011 and 2014 in the National Health Insurance Research Database of Taiwan." (PMID 33194721, 2020). "This study, therefore, aimed to investigate the treatment sequences and clinical outcomes of treatment-naïve, EGFR-mutant advanced lung adenocarcinoma patients receiving TKIs in a real-world, population-based setting." (PMID 33489886, 2020). "Even in mutant EGFR-driven lung adenocarcinoma, dysregulation of EGFR degradation further accelerates tumor initiation and progression." (PMID 32694521, 2020).
lung adenocarcinoma (continued). "To validate the clinical relevance of this study, we compared the expression of Mig-6 in lung adenocarcinoma specimens obtained from patients both before treatment with EGFR-TKIs and after the development of acquired EGFR-TKI resistance." (PMID 32552717, 2020). "Until now, no large-scale clinical data regarding the effect of β-blockers in patients with lung adenocarcinoma receiving EGFR-TKIs is available." (PMID 33194721, 2020). "Herein, a retrospective study was performed using the National Health Insurance Research Database (NHIRD) of Taiwan to investigate the effect of β-blockers on patients with lung adenocarcinoma receiving first-line EGFR-TKIs." (PMID 33194721, 2020). "The lung adenocarcinomas exhibiting integrin upregulation were highly enriched in mutation and mRNA upregulation of KRAS or EGFR, and were linked to poor clinical prognosis compared to those carrying alterations in single oncogene." (PMID 32793596, 2020). "The first case was a 61-year-old man who was an ex-smoker with stage IV lung adenocarcinoma harbouring EGFR exon 19 insertion." (PMID 31956415, 2020). "In the magnetic migration test the KRAS mutant A549 and the EGFR mutant PC-9 lung adenocarcinoma cell lines were used in 3D mono-cultures." (PMID 32434541, 2020). "Conditioned medium from human lung adenocarcinoma HCC827 cells treated with EGFR-TKIs also inhibited HLEC migration and tube formation." (PMID 31892990, 2020). "Our data show that AMs play a more potent role in driving EGFR mutant lung adenocarcinoma development compared with IMs." (PMID 32125091, 2020). "Specifically, ctDNA is an established test for example for EGFR mutant lung adenocarcinoma to both diagnose and follow patients being treated with targeted therapies." (PMID 31947893, 2020). "Specific targeted agents like gefitinib, afatinib, osimertinib (for EGFR mutated tumors) and crizotinib/ceritinib (for ALK rearranged lung adenocarcinomas) have been approved by the Food and Drug Administration (FDA) for clinical use." (PMID 32149365, 2020). "The EGFR impact score can predict the responsiveness to TKI treatment in patients with EGFR mutant lung adenocarcinoma." (PMID 32277151, 2020). "Herein we presented a case of chemotherapy-refractory and EGFR wild-type lung adenocarcinoma that showed significant response to fourth-line anlotinib monotherapy." (PMID 33031343, 2020). "Most driver alterations in lung adenocarcinomas, such as mutations in KRAS and EGFR, ALK fusions, and loss of NF1 function, confer activation of the Ras/Raf/ERK pathway." (PMID 32158759, 2020). "An example of secondary resistance to gefitinib (an epidermal growth factor receptor [EGFR] inhibitor) that is frequently observed in lung adenocarcinoma patients, but only infrequently found in cancer cell lines, is the EGFRT790M mutation." (PMID 33205120, 2020). "This study aimed to reveal the effects of CAPN1/PTPN1 on malignant phenotype and EGFR‐TKI resistance of lung adenocarcinoma (LUAD) cells." (PMID 32395869, 2020). "In this study, EGFR-mutant lung adenocarcinoma patients had better survival rate than patients with wild-type EGFR." (PMID 32053675, 2020). "For example, PC9 lung adenocarcinoma cells harbour an activating EGFR exon 19 in‐frame deletion and are naturally sensitive to the EGFR inhibitor erlotinib." (PMID 32202050, 2020). "Patients with stage IIIB-IV lung adenocarcinoma taking epidermal growth factor receptor (EGFR) TKIs or anaplastic lymphoma kinase (ALK) inhibitors were enrolled prospectively from June 2012 to February 2015." (PMID 33306683, 2020). "B7-H3-induced signaling includes at least three cascades: PI3K/AKT, JAK2/STAT3, and Raf/MEK/ERK1/2, which are also involved in epidermal growth factor receptor- (EGFR-) triggered signaling in lung adenocarcinoma cells." (PMID 33426073, 2020). "We reported five cases of lung adenocarcinoma who developed a mental disorder or conscious disturbance after treatment with EGFR-TKI." (PMID 32256269, 2020).
lung adenocarcinoma (continued). "We use a well‐characterized mouse model of epidermal growth factor receptor (EGFR) mutant lung adenocarcinoma and show that depletion of alveolar macrophages (AMs) has a strong impact on restricting lung tumor progression." (PMID 32125091, 2020). "Herein, we aim to investigate the correlation between certain CA9 SNPs and EGFR variation in patients with lung adenocarcinoma." (PMID 32365566, 2020). "This study aimed to evaluate the effect of β-blockers in patients receiving first-line epidermal growth factor receptor tyrosine kinase inhibitors (EGFR-TKIs) for lung adenocarcinoma." (PMID 33194721, 2020). "Multiple generations of EGFR tyrosine kinase inhibitors (TKIs) have been effective as first-line therapy for advanced EGFR-mutant lung adenocarcinoma patients." (PMID 33489886, 2020). "Subgroup analysis of clinicopathological parameters according to the mutant ctDNA in EGFR-mutant lung adenocarcinoma (n = 15)." (PMID 32196518, 2020). "In this study, we found that the SUV entropy measured from the pretreatment 18F-FDG PET was independently associated with the time-to-progression of EGFR-targeted TKI treatment and the OS in patients with lung adenocarcinoma harboring EGFR mutations." (PMID 33370365, 2020). "Both EGFR and EML4-ALK mutations are mainly seen in lung adenocarcinoma, and these activated oncogenic mutations promote cell survival, proliferation, invasion, and metastasis." (PMID 32923394, 2020). "Integrin αV expression was detected in 7 tumour tissues from lung adenocarcinoma patients before and after EGFR-TKI resistance acquisition." (PMID 33287873, 2020). "In our study, the effects of two different doses of BPAP were studied in a newly developed EGFR wild type mouse lung adenocarcinoma xenograft." (PMID 30734151, 2020). "In conclusion, radiomics signature can help to distinguish between EGFR positive and wild type advanced lung adenocarcinomas." (PMID 32082997, 2020). "Inhibition of PD-L1 can reduce the proliferation and wound healing of EGFR-TKI-resistant lung adenocarcinoma cells." (PMID 33024576, 2020). "One study demonstrated that CLDN-1 expression correlated with Ras and epidermal-growth-factor-receptor (EGFR) expression suggesting the involvement of the latter two signaling pathways in the regulation of CLDN-1 in lung adenocarcinoma." (PMID 31952355, 2020). "In this study, we compared the detection rates of EGFR-tyrosine kinase inhibitor-sensitizing mutations (mEGFRs) in bronchial washing fluid (BWF) and the plasma of patients with lung adenocarcinoma using the tissue genotype as the standard reference." (PMID 32517757, 2020). "Nonetheless, pending prospective validation, our results suggest that compared with TKI treatment alone, RT does significantly improve both PFS and OS in medically inoperable EGFR-mutant adenocarcinoma of the lung compared with TKI alone." (PMID 32660443, 2020). "Epidermal growth factor receptor (EGFR) mutations and anaplastic lymphoma kinase (ALK) rearrangement are the two most common druggable targets in lung adenocarcinoma." (PMID 32690092, 2020). "Our findings reinforce scientific notion of Mig-6 as an oncoprotein in the context of EGFR-TKI resistant lung adenocarcinoma." (PMID 32552717, 2020).
lung adenocarcinoma (continued). "The preliminary data of our study indicate that primary tumor SUV entropy and pleural effusion were early predictive biomarkers of survival in patients with lung adenocarcinoma treated with EGFR-targeted TKIs." (PMID 33370365, 2020). "In the present study, a relationship between response to treatment with EGFR inhibitors in patients with stage IV lung adenocarcinoma, and the expression of EGFR in skin as well as the number of layers in the stratum corneum was found." (PMID 33015988, 2020). "A series of 116 patients with EGFR-positive lung adenocarcinomas were treated with first/second generation EGFR TKIs." (PMID 32215186, 2020). "Characteristics of advanced lung adenocarcinoma patients receiving epidermal growth factor receptor TKIs as first-line systemic therapy." (PMID 33489886, 2020). "All of them provide robust and similar effects in advanced EGFR-mutant lung adenocarcinoma patients." (PMID 33489886, 2020). "In the present study, we found no significantly different frequencies of the FGFR4 SNPs rs2011077, rs351855, rs7708357, and rs1966265 in patients with wild-type EGFR and mutant-type EGFR lung adenocarcinoma." (PMID 32781755, 2020). "This retrospective study included lung adenocarcinoma patients who had a radiographically-confirmed progressive disease under EGFR-TKI treatment and had re-biopsy samples for T790M testing from seven medical centers in Taiwan from June 2013 to December 2018." (PMID 33014788, 2020). "In our clinical center, we found that several patients with advanced lung adenocarcinoma developed a mental disorder or conscious disturbance after EGFR-TKI treatment." (PMID 32256269, 2020). "We further analyzed the potential correlation between the clinicopathologic characteristics of lung adenocarcinoma and the distribution of EGFR phenotype and CA9 SNP rs2071676." (PMID 32365566, 2020). "We used the EGFR mutant doxycycline‐inducible mouse model of lung adenocarcinoma to deplete interstitial or AMs by clodronate‐encapsulated liposomes administered intravenously (IV) and intratracheally (IT), respectively." (PMID 32125091, 2020). "In this study, we tried to clarify the role of Mig-6 in lung adenocarcinoma, especially in context of EGFR-TKI-resistant lung adenocarcinoma and attempted to overcome EGFR-TKI resistance by regulating Mig-6 expression." (PMID 32552717, 2020). "Recently, several real-world studies have investigated the characteristics and clinical effectiveness of these three EGFR TKIs administered in advanced lung adenocarcinoma patients." (PMID 33489886, 2020). "Clinicopathological parameters according to the mutant ctDNA in EGFR or KRAS-mutant lung adenocarcinoma (n = 21)." (PMID 32196518, 2020). "In this study, we found that bone metastasis from EGFR mutant lung adenocarcinoma had lower SUVmax than EGFR wild types." (PMID 32742498, 2020). "By tracking the evolution of lung adenocarcinomas, most BRAF, EGFR, and KRAS activating mutations are trunk drivers." (PMID 32333643, 2020). "A study reported that the PI3K signaling was key to regulate aerobic glycolysis in EGFR-mutant lung adenocarcinoma." (PMID 32595734, 2020). "Comparing the OS of different second-line chemotherapy regimens, pemetrexed was associated with better OS than was vinorelbine in gefitinib users with advanced EGFR mutant lung adenocarcinoma (Ref: pemetrexed, HR: 1.65, 95% CI: 1.28–2.13, p = 0.0001)." (PMID 33489886, 2020). "All these results suggested that ALK probably played a key role in tumor metastasis of multifocal Lung Adenocarcinoma Harboring EGFR/ALK co-alteration." (PMID 32375829, 2020).
lung adenocarcinoma (continued). "The present study identified α5-nAChR as a regulator mediating the tumorigenesis effects of low-dose nicotine on lung adenocarcinoma in aspects of proliferation, migration, epithelial-mesenchymal transition, and EGFR pathway activation." (PMID 32957649, 2020). "EGFR tyrosine kinase inhibitors (EGFR TKIs) are the standard of care treatment for patients with EGFR-mutant lung adenocarcinoma (LUAD)." (PMID 32183160, 2020). "Due to the primary diagnosis of EGFR-mutant lung adenocarcinoma, EGFR-TKI gefitinib was administered and resulted in 1 year of stable disease until the patient developed progression in the right pulmonary nodule with new metastatic cervical lymph nodes." (PMID 32547945, 2020). "Fifty-one of these patients had advanced lung adenocarcinoma and were treated with first-generation EGFR-TKIs as first-line therapy." (PMID 33363040, 2020). "Analysis of a dataset of lung adenocarcinoma specimens from the TCGA database indicated that samples with high BASP1 expression exhibited significantly elevated EGFR signaling (left)." (PMID 33042262, 2020). "In terms of patients, the effective EGFR mutation rate in MPLA patients was 64.2%, which was higher than that in single lung adenocarcinoma patients (27–56%)." (PMID 32690092, 2020). "A prior report identified a subgroup of patients with EGFR-mutant lung adenocarcinoma featuring genomic instability." (PMID 32277151, 2020). "First, we demonstrated that PD-L1 is concurrently expressed on the tumor surface during part of stage IV EGFR mutant lung adenocarcinoma." (PMID 32092879, 2020). "The potential mechanisms involved in dysregulated FGFR4 signaling cascades in Taiwanese patients with lung adenocarcinoma, particularly those with the wild-type EGFR gene, warrant further exploration." (PMID 32781755, 2020). "That is why we tested its efficacy in two different doses in a newly developed EGFR wild type mouse lung adenocarcinoma xenograft model." (PMID 30734151, 2020). "In this study, we also investigated the effect of the ERβ1 expression pattern on PFS in EGFR-mutant lung adenocarcinoma patients." (PMID 33585221, 2020). "In vitro studies have shown that MET amplification in HCC827 lung adenocarcinoma cells, which harbor EGFR 19del, mediates resistance to EGFR-TKIs." (PMID 33363040, 2020). "Daily oral administration of 80 mg osimertinib was initiated to treat the EGFR exon 20 insertion-positive lung adenocarcinoma." (PMID 33080698, 2020). "All 591 patients were diagnosed with lung adenocarcinoma by HE staining and immunocytochemical staining, and EGFR gene detection and DNA quantitative analysis were successfully performed with their pleural effusions." (PMID 32127953, 2020). "We found that patients in wild-type EGFR lung adenocarcinoma with higher FGFR4 expression had shorter overall survival times and five-years survival times compared with those with lower FGFR4 expression (p = 0.008; p = 0.006)." (PMID 32781755, 2020). "Based on TCGA data, pathways activated by EGFR mutations were found in 11% of tumors, K-RAS mutations in 32%, PI3K mutations in 4%, HER2 in 3% and PTEN inactivation in 3% of lung adenocarcinoma samples." (PMID 32971741, 2020). "The combination of erlotinib and crizotinib led to a marked tumor shrinkage (> 50%) in a patient with EGFR-mutant and c-Met-amplified lung adenocarcinoma." (PMID 33244458, 2020). "The second case was a 72-year-old man who was an ex-smoker with stage IV lung adenocarcinoma harbouring EGFR exon 21 L858R." (PMID 31956415, 2020). "A total of 132 cases of medically inoperable stage I to III EGFR mutant lung adenocarcinoma were retrospectively reviewed based on data from 5 centers." (PMID 32660443, 2020).